STAT1 (signal transducer and activator of transcription 1)
Diseases named in the same sentence as STAT1 in open-access papers (continued):
Sharing a sentence is not in itself a finding about the gene and the disease.
tumor (continued). "The type I IFN autocrine loop was also manifested in our experimental setting, since STAT1 phosphorylation was evidenced 1 h after the initial PpIX photoactivation on tumor cells." (PMID 31781113, 2019). "Our group has shown that STAT1-mediated gene regulation within immune effectors is necessary for mediating the anti-tumor effects of IFN-α and also that the amount IFN-α administered to melanoma patients is likely in excess of the optimal biological dose." (PMID 30725205, 2019). "In numerous cancers, STAT1 overexpression has also been suggested to confer resistance to chemotherapy and radiation through the upregulation of IRGs that facilitate tumor cell survival, immune exhaustion through prolonged IFN-γ signaling, and errant growth." (PMID 31842362, 2019). "Overexpression of IFNAR1, MX1 and signal transducer and activator of transcription 1 (Stat1) indicated the endogenous IFNα activation in tumour microenvironment, which correlated with immunosuppression status in HNSCC patients." (PMID 30555157, 2019). "Immunoblot results confirm this observation, revealing that STAT1 activation is also caspase-11 dependent at the tumour development stage." (PMID 30538296, 2019). "They would limit toxicity by using tumor-associated receptors to target IFNs to the TME and suppress STAT3 activation, while simultaneously, activating STAT1/2 in both tumor cells and immune cells." (PMID 31684144, 2019). "Experimental studies in STAT1 knockout mouse have demonstrated a tumor suppressor function mainly through tumor intrinsic and extrinsic mechanisms." (PMID 30456450, 2019). "IF staining in dysplastic colon tissue showed that less STAT1 activation occurred during tumour development in Casp11−/− mice, compared to WT." (PMID 30538296, 2019). "STAT1 signaling activation has been shown in multiple tumor entities to be tumor suppressive and to be involved in therapy resistance mechanisms." (PMID 30886199, 2019). "Consistently, STAT1−/− mice are more prone to tumor development and STAT1 deletion in leukemic cells decreases MHC class I expression." (PMID 31817042, 2019). "Taking these reports into account, dysregulation of STAT1 (upregulation and down-regulation) occurs in tumor cells." (PMID 31569687, 2019). "Gene expression analysis of cells expressing miR-145-5p mimics revealed activation of the Signal transducer and activator of transcription 1 (STAT1) signaling pathway which is mainly tumor suppressive." (PMID 30886199, 2019). "This is surprising, since STAT3 has widely been described as a tumor driver in ALCL and STAT1 has been often ascribed a tumor suppressive function by inducing cell cycle arrest, apoptosis and suppression of metastasis." (PMID 30131584, 2019). "Studies utilising STAT1 knockout mice have consistently reported the acceleration of tumor growth and defective IFN-γ-driven tumor cell killing by NK and T cells, indicating that both innate and adaptive antitumor responses are impaired when STAT1 is lost." (PMID 31842362, 2019). "In contrast, STAT1 was predominantly viewed as an independent tumor suppressor and positive prognostic marker." (PMID 30718461, 2019). "In HCC patients, the majority of STAT1 is unphosphorylated, while phosphorylated STAT1 is responsible for the anti-tumor effect." (PMID 31683891, 2019). "Stat1 is known for its anti-tumor activity, whereas Stat3 is known for promoting tumor progression and immunosuppression." (PMID 31709183, 2019). "Our results indicate that the IFNy-STAT1 signal transduction pathway was impaired in OGD cultured tumor cells." (PMID 31196219, 2019). "In our study, we showed that soft-wired alterations in the IFNy-STAT1 pathway, which were induced by limited nutrient availability in the tumor microenvironment, reduced the IFNy responsiveness and consequent MHC-I antigen presentation of cancer cells." (PMID 31196219, 2019).
tumor (continued). "Compared to the tumor-free tissues, we found higher levels of STAT1 is in the cytoplasm of HCC cells, whereas the levels in nuclear are comparable." (PMID 30456450, 2019). "We then investigated the mechanism by which OGD cultured tumor cells reduced their capacity to respond to IFNy, resulting in impaired STAT1 phosphorylation." (PMID 31196219, 2019). "On the other hand, STAT1 can also be a tumor promoter as it can promote tumor cell growth, therapy resistance, and immune suppression." (PMID 30456450, 2019). "Of note, previous studies have shown that STAT1 activation can promote miR-29 transcription and that miR-29 can decrease tumor cell proliferation by downregulating CDK6, corroborating our western blot data." (PMID 31382461, 2019). "We suggested that chronic infection by P. gingivalis caused secretion of cytokines such as IL6 to initiate OSCC and to activate tumorigenic transcription factors such as STAT1 for tumor progression." (PMID 30847302, 2019). "Further studies showedthat PAR-1 activation-mediated tumor cell apoptosis is associated with tyrosinephosphorylation of JAK2 and STAT1, and translocation of STAT1 to the nucleus." (PMID 30785507, 2019). "Cytokine IL-6, which has a dual role in the anti-tumor immunity, activates signaling proteins Stat1 and Stat3 in addition to its other functions." (PMID 31709183, 2019). "Consistently with the tumor suppressive role of STAT1 signaling in tumorigenesis, nuclear IRF7 protein expression was significantly reduced in GBC compared to normal gallbladder epithelium of paired samples (p < 0.001)." (PMID 30886199, 2019). "IFNy stimulation greatly induced total STAT1 expression in normal, OG, and DG conditions in both tumor cell lines." (PMID 31196219, 2019). "In summary, we demonstrate that endogenous IFNα promotes the expression of PDL1 through IFNAR1/Stat1 in tumour cells and PD1 in immune cells, which contributes to immunosuppression formation in HNSCCs." (PMID 30555157, 2019). "These elevated Stat1 levels seemed to contribute to the tumor surveillance Interferons-I, which were found to systemically activate natural killer cell activity." (PMID 30621584, 2019). "The enhanced tumor burden was associated with reduced levels of both IL-1β and IL-18 which resulted in reduced STAT1 signaling and sub-optimal anti-tumor type I immunity." (PMID 31231388, 2019). "While STAT2 and STAT4 promote the anti-tumor immune response, STAT3 and STAT6 mediate immunosuppression in the TME, and STAT1 and STAT5 have been implicated in both activation and suppression of the anti-tumor immune response." (PMID 31057536, 2019). "The dynamic induction of p-STAT1 and u-STAT1 by IFN treatment coordinately regulates the growth of tumor cells." (PMID 30456450, 2019). "Increased angiogenic markers and decreased IEC death were also observed in Casp11−/− tumours, processes which are usually inhibited by STAT1." (PMID 30538296, 2019). "PIAS1 is reported to play a crucial role in the proliferation of PCa cells, possibly through regulation of NFκB and STAT1, which are known regulators of cellular proliferation and apoptosis in several tumour models." (PMID 31639157, 2019). "An examination of STAT protein expression levels showed that STAT6 levels were significantly lower in GSCs compared with non-tumor tissue, whereas levels of STAT1, STAT3 and STAT5 were significantly higher." (PMID 31530290, 2019). "As the active form of STAT1, p-STAT1 has been widely recognized as the functional form in inhibiting tumor growth through inducing cell apoptosis and regulating cell cycle." (PMID 30456450, 2019). "STAT1 was initially considered to exert tumor suppressor functions, and its oncogenic potential emerged more recently." (PMID 31694222, 2019). "Collectively, we found that cytoplasmic STAT1 expression in tumor tissues appears higher compared to tumor-free tissues." (PMID 30456450, 2019).
tumor (continued). "We have recently reported that PD-L1 is overexpressed in human tumor tissues and dual inhibition of signal transducers and activator of transcription 1 (STAT1) and STAT3 can downregulate PD-L1 expression." (PMID 30915120, 2019). "Accumulated evidence indicated that Stat1 mediates anti-proliferative effects by inducing upregulation of cell cycle inhibitors and apoptosis genes in several tissues and Stat1-null mice are more prone to tumor development than controls." (PMID 29796172, 2018). "IGFBP3 also has been shown to facilitate GBM tumor cell proliferation, invasion, and migration through the regulation of STAT-1 signaling." (PMID 30231881, 2018). "Accumulating evidence indicates the emerging role of STAT1 in tumor growth, immune suppression, and therapeutic resistance." (PMID 29765155, 2018). "IFN-γ is described as an antiproliferative agent that regulates the expression of cyclin-dependent kinase inhibitor 1 (p21) through STAT1 activation in tumor cells." (PMID 29780381, 2018). "STAT1 has been reported for its tumor suppressive as well as tumor promoting functions, whereas TGF-β inhibits cell proliferation at an early stage and promotes invasion and metastasis at the later stage of cancer." (PMID 29751820, 2018). "The present study further showed that cANGPTL4 mainly regulates tumor cell proliferation, and induces STAT1 production depending on sarcoma gene (Src) /MAPK signaling pathway activation." (PMID 30049845, 2018). "STAT1 has been known to contribute to tumor development in various cancer types through complicated ways." (PMID 30150751, 2018). "Multiple immune-regulatory interferon-related genes as well as STAT1/2 (Signal Transducer and Activator of Transcription) in particular, which plays a key role in tumor progression and immune-modulation, were present in this overlap region." (PMID 30018734, 2018). "In advanced stages of tumor development, at Days 40 and 68, the number of Ki67+ cells also increased in both WT and STAT1−/− AOM/DSS treated mice." (PMID 30235866, 2018). "It has been well-established that the IFN-γ-induced upregulation of PD-L1 expression in tumor cells is mediated transcriptionally through the activation of signal transducer and activator of transcription 1 (STAT1) downstream of the IFN-γ receptor." (PMID 30373602, 2018). "To get mechanistic insight, we analyzed sex‐specific STAT1 effects on tumor parameters, STAT3 activation, and expression of STAT1 target genes implicated in tumorigenesis." (PMID 29419930, 2018). "Several recent studies have reported that IFN-γ induces PD-L1 expression in tumor cells by activating STAT1 signaling, suggesting a possibility on the effectiveness of immunotherapy targeting IFN-γ-induced PD-L1 expression." (PMID 30400799, 2018). "Following CAC induction, STAT1−/− mice displayed an accelerated appearance of inflammation and tumor formation, and increased damage and scores on the disease activity index (DAI) as early as 20 days after AOM-DSS exposure compared to their WT counterparts." (PMID 30235866, 2018). "In summary, our data demonstrate that expression of tumor cell‐intrinsic nuclear STAT1 protein is a male‐specific prognostic factor in human CRC." (PMID 29419930, 2018). "Another STAT family member, STAT1, is considered to be a tumor suppressor that reduces proliferation, induces apoptosis, and enhances cancer immunosurveillance." (PMID 29765155, 2018). "A previous study showed that CRC cell lines with a low STAT1/high STAT3 ratio presented faster tumor growth when they were xenografted into SCID mice." (PMID 30235866, 2018). "Tumor cells derived from STAT1−/− mice retain ER and PR expression and E2 is required for successful engraftment and progression of subsequent tumor transplants that resemble luminal-like human breast cancers." (PMID 30338425, 2018). "Most importantlysignificantly increased expression of Stat1(6.6-fold increase) and Cxcl10 (3.5-foldincrease) were noted in the tumours from STING agonist-treated mice." (PMID 30046165, 2018).
tumor (continued). "This strategy significantly improved the prognostic value of STAT1 in the male cohort but abolished it in the female cohort indicating that tumor cell‐intrinsic nuclear STAT1 suppresses CRC progression in male but not in female patients." (PMID 29419930, 2018). "STAT-1 behaves as a tumor suppressor through promotion of apoptosis as well as inhibition of angiogenesis, tumor growth, and metastasis." (PMID 30279968, 2018). "On the other hand, STAT1 also plays a critical role by inducing antiproliferative and proapoptotic activities which hampers tumor growth." (PMID 29854771, 2018). "STAT1, as a tumor suppressor, is deducted for its expression in tumor cells, modulates their immunological status and consequently their response to antitumor immune responses." (PMID 29780381, 2018). "STAT1 is commonly considered as a tumor suppressor as observed in murine sarcomas and several mouse breast cancer models." (PMID 29419930, 2018). "STAT1 has been reported as a tumor suppressor in multiple cancers by inhibiting tumor cell angiogenesis, tumorigenicity and metastasis." (PMID 29855346, 2018). "When IFN-α binds to its receptor, the JAK/STAT pathway is activated and STAT1 is subsequently phosphorylated and acts as an anti-tumor activator." (PMID 30167088, 2018). "A sex‐specific stratification of human CRC patients corroborated the data obtained in mice and revealed that reduced tumor cell‐intrinsic nuclear STAT1 protein expression is a poor prognostic factor in men but not in women." (PMID 29419930, 2018). "STAT1 deletion will change the interactions between tumor and fibroblast cells and contribute to CC progression, suggesting that STAT1 is an important link between intestinal inflammation and CC." (PMID 30013563, 2018). "We evaluated the course of the disease for 20-, 40-, and 68-day periods in STAT1−/− and WT mice as an approximation of different stages of tumor progression." (PMID 30235866, 2018). "An association between nitric oxide elevation and increased levels of nitration on STAT1 in splenocytes from tumor-bearing mice was observed." (PMID 30405034, 2018). "The PDL1 expression on tumor cells can be upregulated by intrinsic oncogenic signaling pathways or by surrounding T cells through the IFNγ/STAT1/IRF1 pathway and chronic type I IFN exposure." (PMID 30305853, 2018). "Studies in mice and data from human patients have suggested that STAT1 has tumor suppressor properties; however, there is growing evidence that it can also act as a tumor promoter." (PMID 30235866, 2018). "Survival analyses demonstrated that tumor cell‐intrinsic nuclear STAT1 protein expression is a beneficial prognostic factor in CRC." (PMID 29419930, 2018). "As tumor suppressor protein, STAT1 (Signal transducer and activator of transcription 1) inhibits a range of tumor growth and induces cell apoptosis." (PMID 29707241, 2018). "Recent studies have tried to explore the factors influencing PD-L1 expression, and demonstrated that IFN-γ promotes PD-L1 expression on macrophage and tumor cells in a STAT1- or PDK2-dependent manne." (PMID 29593314, 2018). "Upstream regulatory analysis implicated increased activation of STAT1 and IRF1, and inhibition of Interferon-stimulated transcription mediated by IRF4, in hot tumours." (PMID 30104673, 2018). "STAT1−/− mice showed elevated colonic epithelial cell proliferation in early stages of injury-induced tumor formation and decreased apoptosis in advanced tumors with over-expression of the anti-apoptotic protein Bcl2 at the colon." (PMID 30235866, 2018). "In accordance with this finding, we observed increased cell proliferation at the initial steps of tumor development in STAT1−/− CAC-induced colons, consistent with more signs of the disease, damage, and reduced survival." (PMID 30235866, 2018). "Our data demonstrate that epithelial STAT1 is a sex‐specific tumor suppressor in CRC of mice and humans." (PMID 29419930, 2018).
tumor (continued). "STAT1 also directly controls immune suppression by upregulating the expression of PD-L1 on tumour cells." (PMID 28276425, 2017). "The density of tumor-infiltrated macrophages was significantly higher in the tumors engrafted into a WT host than either the KO host or the spontaneous Stat1-null tumors." (PMID 28865492, 2017). "When activated, STAT1 suppresses tumour development by inducing apoptosis and also inhibit tumour angiogenesis." (PMID 28344639, 2017). "All MT/Shc2F/2F tumours displayed an IFNγ-inducible increase in nuclear STAT1 levels relative to MT/ShcA+/+ and MT/Shc313F/313F tumours, which are immunosuppressive." (PMID 28276425, 2017). "When these Stat1−/− mice are crossed with Neu-expressing GMM, the resulting bigenic animals do, however, exhibit accelerated tumorigenesis, suggesting that STAT1 functions as a tumor suppressor." (PMID 28865492, 2017). "Signal transducer and activator of transcription 1 (STAT1), which is usually regarded as a transmitter of interferon signaling and a pro-apoptotic tumor suppressor, has also been found to be associated with the Warburg effect." (PMID 27823965, 2017). "On the one hand, STAT1/3 mediates TNFα-induced senescence by promoting expression of anti-proliferative, inflamma-tory, and tumor suppressor genes involved in main-taining the senescent state." (PMID 29176033, 2017). "STAT1 staining was strong to moderate in both tumor and stromal regions in the majority of Push/LPC tumors; whereas, most of the Inf/FMX tumors exhibited mild to absent staining of STAT1." (PMID 29225558, 2017). "Our cell culture experiments suggest that Stat1-null tumor cells secrete both macrophage migration-promoting and macrophage migration-inhibiting factors, though we cannot distinguish between a direct and indirect microenvironmental effect." (PMID 28865492, 2017). "In conjunction with our previous publication that STAT1 is a tumor suppressor in ESCC, results from this study strongly supports the concept that ERK suppresses the expression of STAT1 in ESCC." (PMID 28431406, 2017). "Consistently, p-STAT3 expression level was high in poorly differentiated region of HNSCC, whereas STAT1 level was high in well-differentiated tumor region." (PMID 28270740, 2017). "By contrast, natural killer (NK) cell activation and secretion of IFN-γ significantly enhanced PD-L1 expression by activating JAK1, JAK2, and STAT1 in tumor cells." (PMID 27974689, 2017). "STAT1 has been reported as a potential tumor suppressor and regulator of the anti-proliferative/pro-apoptotic responses in tumor cells." (PMID 29371942, 2017). "An increased level of STAT1 has been reported as conferring cellular resistance to DNA-damaging agents and mediating tumor growth aggressiveness." (PMID 28751665, 2017). "The STAT1 protein, composed of 750 amino acids with a size of 91 kDa, has been classified as a tumor suppressor." (PMID 28282916, 2017). "Macrophages exposed to CM from the Stat1-null tumor cell line SSM2, compared with CM from the other three cell lines, had shorter track lengths for each time-lapse interval and moved more slowly." (PMID 28865492, 2017). "It has been demonstrated that the anti-tumor effects of IFN-α were dependent on STAT1 signal transduction in immune cells via phosphorylation of tyrosine 7018." (PMID 29133913, 2017). "STAT1 has been considered a tumor suppressor through mechanisms of increased anti-tumor immune response, and STAT1 expression has been associated with improved outcomes in cancer." (PMID 29225558, 2017). "STAT3 plays a major role in promoting tumor immune evasion since it not only has opposite effects to immunostimulatory STAT1 but also induces the secretion of immunosuppressive soluble cytokines that induce a tolerant TME." (PMID 28611673, 2017). "In turn, the cytokines act as paracrine factors that promote tumour growth and chemoresistance through signal transducer and activator of transcription 1 (STAT1) and NF-κB." (PMID 28098771, 2017).